EIF4E (eukaryotic translation initiation factor 4E)
Diseases named in the same sentence as EIF4E in open-access papers (continued):
Sharing a sentence is not in itself a finding about the gene and the disease.
colon carcinoma (20 papers, 2010 to 2023). "In summary, our findings indicated that the levels of eIF4E and αvβ6 expression are elevated in colonic carcinoma, which were associated with tumor progression and poor prognosis of patients with colon cancer." (PMID 24839543, 2014). "Recent studies showed that miR-145 silenced c-Myc and its downstream targets in colon cancer, which be associated with c-Myc/eIF4E as a miR-145 target." (PMID 21092188, 2010). "OSI-027 is an inhibitor of mTOR downstream of PI3K and can inhibit colon cancer cell growth through the 4EBP1/eIF4E/PUMA pathway." (PMID 36414988, 2022). "Although not significant, mRNA expression levels of ENOPH1, RANBP1 and EIF4E were higher in BRAFV600E mutant colon cancer than in the unaltered group." (PMID 34201061, 2021). "Since many of these proteins including NPM1, RanBP1, eIF4E and PSPH were previously reported to be transcriptional targets of c-Myc, expression of c-Myc in colon cancer cell lines differing in their BRAF mutational status was also examined." (PMID 34201061, 2021). "It has been shown, that eIF4E plays an important role in the nucleocytoplasmic export of human iNOS mRNA in colon carcinoma cell line." (PMID 32731559, 2020). "Eukaryotic translation initiation factor 4E (eIF4E) is a translational regulator; expression of eIF4E in human colon cancer cells promotes the TGFβ stimulation of adhesion molecules." (PMID 28061442, 2017). "The results showed that eIF4E was able to promote the metastasis of colon cancer cells both in vivo and in vitro." (PMID 27907907, 2016). "We found that the overexpression of eIF4E significantly promoted the metastasis and self-renewal of the colon cancer cell line SW480." (PMID 27907907, 2016). "It is suggested that the regulation of eIF4E should be a potential target for preventing colon cancer invasion and metastasis." (PMID 27907907, 2016). "Both eIF4E and integrin αvβ6 can play important roles in the development and progression of colonic carcinoma." (PMID 24839543, 2014). "eIF4E and Integrin αvβ6 were indicators of tumor’s progression and poor prognosis of patients with colon cancer." (PMID 24839543, 2014). "eIF4E S209 promotes colon cancer growth in vivo through Myc and the ISR." (PMID 33135632, 2020). "Using EIF4E S209A/+ knockin (4EKI) human colon cancer cells and mice, human CRC organoids and adenoma samples, we uncovered a key role of p-4E in Myc and ATF4 translation, which promotes ISR-dependent glutamine metabolism, AKT signaling and oncogenic proliferation." (PMID 33135632, 2020). "We also investigated the function of eIF4E in the metastasis of colon cancer in vivo and in vitro." (PMID 27907907, 2016). "The aim of our present study was to explore the coexpression and clinical significance of eIF4E combined with integrin αvβ6 in colon cancer, which could provide a theoretical basis for further study of molecular mechanism in therapeutic intervention." (PMID 24839543, 2014). "The results suggested that eIF4E may be taken as potential target for colon cancer treatment." (PMID 27907907, 2016). "In the current study, we incubated human colon cancer HCT116 cells with vanillic acid, the results showed that vanillic acid inhibited p-mTOR, p-p70S6K, p-4E-BP1, and p-eIF4E protein expression levels." (PMID 30678221, 2019). "Analysis of TCGA colon cancer (n=461) and skin cancer (n=470) datasets revealed a positive correlation between PHF14 expression and protein translation initiation factors, eIF4E, eIF4B, and RPS6." (PMID 31040906, 2019). "We found that eIF4E, VEGF-C and MMP-2 were up-regulated in colon cancer, and their expression frequencies are higher in cancerous tissues than in normal control tissues." (PMID 27907907, 2016).
colon carcinoma (continued). "We next investigated the effect of eIF4E, VEGF-C, MMP-2 and E-cadherin on lung metastasis of colon cancer cells in mouse model, which mimics the clinical status of tumor metastases to distant sites." (PMID 27907907, 2016). "The result suggested that overexpression of eIF4E, VEGF-C, and MMP-2 promote the colon cancer cell growth." (PMID 27907907, 2016). "We furthermore investigated the expression of eIF4E, VEGF-C, MMP-2 and E-cadherin in primary site of patient-derived colon cancer xenografts." (PMID 27907907, 2016). "Among these protein factors, eIF4E dominates the regulation of VEGF-C, MMP-2 and E-cadherin, and is a key factor for colon cancer metastasis." (PMID 27907907, 2016). "Utilizing the stable HCT-15/Rluc cell lines (HCT-15/RLuc/eIF4E, HCT-15/Rluc/VEGF-C, HCT-15/Rluc/MMP-2, HCT-15/Rluc/E-cadherin and parental HCT-15/Rluc), we investigated the effect of eIF4E, VEGF-C, MMP-2 and E-cadherin on the colon cancer cell growth." (PMID 27907907, 2016). "The result suggested that eIF4E, VEGF-C, MMP-2 promote the lung metastasis of colon cancer." (PMID 27907907, 2016).
ovarian carcinoma (19 papers, 2015 to 2025). A malignant neoplasm originating from the surface ovarian epithelium. "The increased expression of eIF4E was also significantly associated with poor prognosis in ovarian cancer (OS HR = 1.1810, 95% CI = 1.02–1.36, P = 0.026)." (PMID 34876062, 2021). "In addition, clinical data indicate that elevated total eIF4E levels along with increased phosphorylation of 4EBP1 is associated with disease progression and poor patient survival in breast, prostate and ovarian cancers.." (PMID 28415825, 2017). "eIF4E and eIF4A1 were also present in EVs isolated from multiple human and murine ovarian cancer cell lines." (PMID 40820860, 2025). "Our data show that the presence of eIF4E in ovarian cancer derived EVs underscores its functional significance in these vesicles." (PMID 40820860, 2025). "Future research should explore how pretreatment plasma EV eIF4E levels, combined with other molecular datasets, can refine treatment stratification and guide personalized therapeutic strategies in ovarian cancer." (PMID 40820860, 2025). "Here, it is revealed that ovarian cancer cells release extracellular vesicles enriched with eIF4E, which alters protein production in macrophages." (PMID 40820860, 2025). "We also compared our proteomic data with the ExoCarta database and identified the presence of both eIF4E and eIF4A1 in EVs derived from ovarian cancer cells." (PMID 40820860, 2025). "Our findings also revealed elevated expression of eIF4E in plasma‐derived EVs from ovarian cancer patients." (PMID 40820860, 2025). "The mTOR signaling pathway is frequently overactivated in ovarian cancer and converge to the increased levels of cap-dependent translation, being eIF4E the focal point of this pathway." (PMID 35582305, 2021). "The increasing evidence that eIF4E targeting slows down cancer progression is having a prompt response in ovarian cancer research." (PMID 35582305, 2021). "We further studied the correlation between the expression of eIF4E and cyclin D1 proteins and clinicopathological features of ovarian cancer, including age, clinical stage, lymph node metastasis status, and survival status by a univariate chi-squared test." (PMID 33489719, 2020). "The results also showed that strong positive expression of eIF4E was related to the survival status of ovarian cancer patients (P = 0.001)." (PMID 33489719, 2020). "The positive expression rate of eIF4E and cyclin D1 in ovarian cancer tissues was 68.3% (84/123) and 64.2% (79/123), respectively." (PMID 33489719, 2020). "We further analyzed the correlation between the expression rates of eIF4E and cyclin D1 proteins in ovarian cancer using Spearman's rank correlation test." (PMID 33489719, 2020). "p-eIF4E overexpression resulted in resistance, whereas eIF4E depletion sensitized ovarian cancer cells." (PMID 32340135, 2020). "Spearman's rank correlation test showed that there was a significant positive correlation between the eIF4E and cyclin D1 proteins in ovarian cancer." (PMID 33489719, 2020). "This eIF4E-targeting peptide was further merged with an analogue of gonadotropin-releasing hormone (GnRH), which is expressed in the majority of ovarian cancer patients and is known for its anti-cancer effects." (PMID 32967226, 2020). "They observed increased phosphorylation levels of ERK, MNK1, and eIF4E in ovarian cancer cells exposed to chemotherapy, as well as in ovarian cancer patients." (PMID 32340135, 2020). "We examined the cellular location and expression level of eIF4E and cyclin D1 proteins in ovarian cancer tissues by IHC." (PMID 33489719, 2020). "In ovarian cancer, 4EBP-based therapeutic peptides can bind eIF4E to prevent its cap-dependent translation, thereby disrupting tumor growth." (PMID 32967226, 2020).
ovarian carcinoma (continued). "Ribavirin is already known to be effective in cancer therapy; it targets an oncogene, the eukaryotic translation initiation factor eIF4E, elevated in approximately 30% of cancers, including many leukemias and lymphomas, breast, esophagea, and ovarian cancers." (PMID 31825993, 2019). "A previous study has reported 4EBP-based eIF4E-binding peptides that prevent eIF4E from binding eIF4G, block cap-dependent translation, and inhibit cell growth in ovarian cancer cells." (PMID 27668427, 2016). "For example, increased EIF5A2 expression is an independent molecular marker for reduced survival in patients with ovarian carcinoma 22 and EIF4E is a useful marker for malignant transformation of cervical squamous cells." (PMID 28203520, 2016). "Moreover, a significant increase in the expression of eIF4E and eIF4A1 in EVs from the plasma and ascites of ovarian cancer patients was observed, compared to EVs from the plasma and pelvic wash of healthy donors." (PMID 40820860, 2025). "Importantly, our study demonstrates that inhibiting EV secretion reduces PD‐L1 expression on TAMs in ovarian tumor bearing mice, highlighting the role of eIF4E in modulating PD‐L1 expression and influencing metastasis in ovarian cancer." (PMID 40820860, 2025). "The upregulation of mammalian target of rapamycin (mTOR), a master regulator of translation initiation, results in the increased expression of cancer-promoting genes such as eIF4E, a limiting factor for translation initiation in most cancers, including ovarian cancer." (PMID 37842240, 2023). "Inhibition of eIF4E by ribavirin may be a potential therapeutic approach to improve clinical management of ovarian cancer." (PMID 35574327, 2022). "JingJin and colleagues found an overexpression of eIF4E in most ovarian cancer patients." (PMID 35574327, 2022). "Thus, specific inhibitors targeting mTOR and eIF4E represent promising and valid adjuvants for clinical management of ovarian cancer." (PMID 35582305, 2021). "Recently, a novel strategy to specifically target eIF4E activity in ovarian cancer models has been reported, where 4E-BP1 peptides were fused to an agonist of the gonadotropin-releasing hormone (GnRH), thereby mediating the uptake and showing a marked decrease in tumor cells growth." (PMID 35582305, 2021). "This minireview explores the possibility of targeting mTOR and eIF4E proteins, thus impacting on translation initiation in ovarian cancer, describing the most promising experimental strategies and specific inhibitors that have been shown to have an effect on other kinds of cancers." (PMID 35582305, 2021). "In ovarian cancer, eIF4E might be a valuable biomarker to predict poor prognoses and a potential therapeutic target to develop valid treatment strategies." (PMID 33489719, 2020). "Strong positive staining of eIF4E was found in the cytoplasm and nucleus of ovarian cancer tissues." (PMID 33489719, 2020). "We wanted to study the localization of eIF4E in ovarian cancer cells under the effect of SRO-91." (PMID 31825993, 2019). "Taken together, these studies suggest that eIF4E represents a promising candidate for the research on ovarian tumors, whereas downregulating eIF4E expression might be a useful and feasible approach to improve the therapeutic responsiveness of ovarian cancer." (PMID 35582305, 2021). "eIF4E was found to inhibit aldehyde dehydrogenase (ALDH) activity and increase the ferroptosis sensitivity of ovarian cancer cells by accumulating lethal lipid peroxidation." (PMID 37842240, 2023). "However, whether overexpression of eIF4E is associated with the development and progression of ovarian cancer has not been reported." (PMID 33489719, 2020).
ovarian carcinoma (continued). "Regulation of eIF4E by the AKT pathway has been demonstrated in gastric, lung and ovarian cancers." (PMID 37217473, 2023). "The expression rate of eIF4E and cyclin D1 in ovarian cancer tissues was significantly higher than that in noncancerous epithelial ovarian tissues (P = 0.001 and P = 0.032, respectively)." (PMID 33489719, 2020). "The results showed that the expression rates of eIF4E and cyclin D1 proteins in ovarian cancer tissues were significantly higher than those in noncancerous epithelial ovarian tissues (P = 0.001 and P = 0.032, respectively)." (PMID 33489719, 2020). "Moreover, the positive expression of eIF4E and cyclin D1 proteins was not related to the age of ovarian cancer patients (P > 0.05, respectively)." (PMID 33489719, 2020).
glioma (18 papers, 2012 to 2025). A benign or malignant brain and spinal cord tumor that arises from glial cells (astrocytes, oligodendrocytes, ependymal cells). "The role of eIF4E in glioma is only simply revealed, and the underlying pathways and mechanisms are worthy of exploration." (PMID 36225177, 2022). "eIF4E/4E-BP1 association controlled by PI3K/Akt/mTOR pathway is a critical step in the translation initiation making this pathway an interesting target for gliomas treatment." (PMID 31795417, 2019). "Survival analysis showed shorter overall survival and disease-free survival in glioma patients with high EIF4E expression." (PMID 39649886, 2024). "Western blot results showed a significant reduction in EIF4E expression after PBK knockdown in glioma cell line HS683." (PMID 39649886, 2024). "Other experiments showed that ribavirin decreased eIF4E activity in glioma and GSCs by decreasing ERK and eIF4E Ser209 phosphorylation." (PMID 36994107, 2023). "This study mainly discussed eIF4E gene expression in glioma and its sensitivity to oxidative stress (OS)." (PMID 36225177, 2022). "To determine the protective action of eIF4E against OS in glioma cells, we treated U251 cells with H2O2." (PMID 36225177, 2022). "This study is the first to demonstrate that eIF4E is overexpressed in glioma clinical samples and cells and that overexpression of eIF4E is significantly linked to adverse prognosis in such patients." (PMID 36225177, 2022). "In glioma samples from the TCGA database, eIF4E showed obviously elevated levels in LGG and GBM patients, which was usually associated with adverse patient prognosis (P < 0.05)." (PMID 36225177, 2022). "Relevant data from The Cancer Genome Atlas (TCGA) database regarding eIF4E gene expression and its prognostic significance in glioma samples were analyzed." (PMID 36225177, 2022). "qPCR and Western blot analyses revealed statistically regulated eIF4E mRNA and protein levels in glioma cell lines compared with HBE cells (P < 0.05), with the highest upregulation found in U251 cells." (PMID 36225177, 2022). "In a previous study, we found that the natural terpene derivative borneol inhibited HIF-1α in primary glioma cells by regulating the mTORC1/eIF4E pathway, and induced autophagy and apoptosis." (PMID 34917504, 2021). "Taken together, borneol sensitized glioma cells to radiation by targeting the mTORC1/eIF4E/HIF-1α pathway." (PMID 34917504, 2021). "The expression levels of HIF-1α, mTORC1 and eIF4E in glioma tissues was markedly lower in the animals treated with borneol and/or radiation compared to the untreated tumor-bearing group (P<0.05 or P<0.01)." (PMID 34917504, 2021). "Consistent with this, borneol significantly downregulated HIF-1α, mTORC1 and eIF4E in the irradiated human glioma primary culture cells, and the inhibitory effect of the combination therapy was stronger compared to radiotherapy alone." (PMID 34917504, 2021). "In conclusion, borneol sensitized glioma cells to radiation by accelerating autophagic cell death through the mTORC1/eIF4E/HIF-1α axis, and should be considered for the treatment of advanced gliomas." (PMID 34917504, 2021). "Consistent with this, silencing of either mTORC1 or eIF4E significantly decreased the levels of HIF-1α in glioma cells, and increased that of LC3 and Beclin-1." (PMID 34917504, 2021). "In a previous study, we showed that borneol inhibited HIF-1α in primary human glioma cells and rat glioma tissues by targeting the mTORC1/eIF4E pathway, which is also involved in autophagy regulation." (PMID 34917504, 2021). "Our findings suggest that borneol sensitizes glioma cells to radiation by inducing autophagy via inhibition of the mTORC1/eIF4E/HIF-1α regulatory axis." (PMID 34917504, 2021). "It was further discovered that in the human primary cultured glioma cells borneol regulated HIF-1a expression via mTORC1/eIF4E pathway." (PMID 32626528, 2020).